MDM2 (MDM2 proto-oncogene)
Diseases named in the same sentence as MDM2 in open-access papers (continued):
Sharing a sentence is not in itself a finding about the gene and the disease.
tumor (continued). "Co-treatment with Nutlin-3 and Bcl-2 inhibitor ABT-737 has been shown to greatly enhance the sensitivity to apoptosis of cancer cells with high MDM2 levels, suggesting that the combined inhibition of MDM2 and Bcl-2 could be a multi-target-based anticancer strategy to trigger tumor death." (PMID 27019364, 2016). "Thus, innovative approaches that convert the clinical response from stable disease to reduced tumor volume could establish a key proof‐of‐concept for drugging MDM2 in human cancer." (PMID 27273042, 2016). "Finally, inhibitors that simultaneously interfere with the action of Mdm2 and its heterodimerization partner MdmX/Mdm4 were recently published, again showing a broader activity against tumor cells, and may thus warrant combination strategies with Wip1i." (PMID 27183917, 2016). "Thus far, most of the published studies focus on MDM2-mediated tumor cell apoptosis." (PMID 27869779, 2016).
tumor (continued). "In addition, our model suggested that GSK3-β might play a tumour suppressor role in CAC by inhibiting CYCLIND1 and MDM2 in the pro-tumor inflammatory microenvironment." (PMID 26446703, 2015). "Hence, if MDM2 is detached from them, they can resume their tumor suppressor action." (PMID 27386018, 2015). "Towards the goal of preempting resistance to MDM2 inhibition and eliciting long term disease control, a cell-based screen was conducted to identify compounds that might synergize with MDM2 inhibitors in the inhibition of tumor cell viability." (PMID 24810962, 2014). "In addition, positive expression of murine double minute 2 (MDM2) was observed in the tumor cells." (PMID 24444015, 2014). "However, in contrast to Myc-driven tumor development, loss of one allele of Arf did not rescue the delay in tumor development caused by an Mdm2 haploinsufficiency." (PMID 23029416, 2012).
tumor (continued). "Coexpres-sion of p21WAF1/CIP1 and MDM2 characterizes serous borderline tumors of the ovary and their implants, which suggests that these cell cycle control proteins are important in these tumors and may be related to tumor progression." (PMID 18665245, 2008). "They first tested whether the tumours showed amplification of Mdm2." (PMID 14966536, 2004). "Similar to scRNA-seq, the expression levels of MDM2 and SESN1 in patients with tumor increased significantly after surgery." (PMID 40335909, 2025). "Preclinical studies have shown that combining MDM2 inhibitors with other therapeutic agents, such as chemotherapy or targeted inhibitors of MYC, can synergistically suppress tumor growth and overcome drug resistance." (PMID 40076599, 2025). "Both MDM2 (a murine double-minute gene indicator) and CDK4 (cyclin-dependent kinase 4) were expressed in the tumor cells." (PMID 40926903, 2025). "So, we utilized NIFE to inhibit NFATc1 and demonstrated that it exerts anti-tumor effects by suppressing both the NFATc1/NADK and NFATc1/MDM2 signaling pathways." (PMID 41203626, 2025). "Advances in nanotechnology-based drug delivery can optimize solubility, stability, and tumor targeting, while nucleic acid therapeutics, including siRNA, CRISPR, and aptamers, offer precision in modulating MDM2 activity." (PMID 41170373, 2025). "Heatmap clustering of subtype-specific and oncogenic-pathway-related genes revealed that PDTOs from patients 1 and 2 closely mirrored their tumor tissues, particularly in the expression of CDK4, MDM2, and myelocytomatosis oncogene (MYC)." (PMID 41376821, 2025). "Resistance alterations were evident in the recurrent tumor: high-level PDGFRA amplification (111 copies) and an in-frame MDM2::PDGFRA fusion – exon 1 of MDM2 (NM_001145339.2, breakpoint 15 bp into exon 1) joined in-frame to exon 8 of PDGFRA (NM_006206.6)." (PMID 40819143, 2025).
tumor (continued). "The study provides the basis to evaluate the therapeutic applicability of anti-mdm2 PROTAC degraders in an appropriate preclinical in-vivo setting, for example in humanized tumor mice." (PMID 40452017, 2025). "Together, these data define a heterogeneous tumor composed of EGFR-amplified, PDFGRA-amplified, and MDM2::PDFGRA-harboring clones." (PMID 40819143, 2025). "Pharmacological inhibition of MDM2 enhances dendritic cell activation, increases CD8+ T cell cytotoxicity, and shifts the CD8+/Treg balance to favor anti-tumor immunity (Wang HQ." (PMID 41170373, 2025). "ecDNA amplifications that harbor driver oncogenes such as EGFR, MYC, MDM2, and CDK4 were detected in 17.1% of 39 human tumor subtypes, including GBM24." (PMID 40678238, 2025). "This study explores the combined application of the MDM2 inhibitor (RG7388) and the STAT3 inhibitor (BBI608) to assess their potential to enhance apoptosis and inhibit tumor growth in ALL cells." (PMID 40943567, 2025). "By stabilizing MYC, MDM2 indirectly supports the upregulation of angiogenic factors such as VEGF, fostering the development of a robust vascular network that sustains tumor growth and facilitates invasion." (PMID 40076599, 2025). "To illustrate the diagnostic and clinical challenges posed by HMGA2-altered neoplasms neoplasms, we first present an index case involving an HMGA2 alteration and MDM2 co-amplification." (PMID 40338436, 2025).
tumor (continued). "There are multiple therapeutic approaches that aim to target MDM2 and CDK4 activity with the aim to restore the intrinsic tumor suppressor cellular response and to terminate oncogenesis." (PMID 40165894, 2025). "The purpose of this study was to synthesize a series of PMI-M3 dual-targeting MDM2/MDMX-based staple peptides by solid-phase synthesis, purify and lyophilize the pure products, and then measure the anti-tumor cell activity." (PMID 38911993, 2024). "Patients with MDM2/MDM4 amplification were taken off immunotherapy in less than two months, and four showed a clearly accelerated rate of tumour growth compared to that before treatment." (PMID 39530091, 2024). "Patients with MDM2/MDM4 amplification developed TTF <2 months and showed a clearly accelerated rate of tumor growth compared to that before treatment." (PMID 39530091, 2024). "By targeting MDM2, APG-115 not only inhibits tumor growth but also reduces the apoptosis of tumor-infiltrating CD8+ T lymphocytes." (PMID 39223632, 2024). "The tumor cells exhibited positive staining for CD21, CD23, somatostatin receptor 2 A, and MDM2 expression." (PMID 38297323, 2024). "Patients with MDM2/4 amplification developed TTF <2 months and showed a clearly accelerated rate of tumor growth compared to that before treatment." (PMID 39530091, 2024). "Another MDM2 inhibitor, APG-115, was also shown to enhance the anti-tumor activity of anti-PD-1 therapy in syngeneic mouse models." (PMID 39272927, 2024). "Similarly, the anti-oncogenic role or tumor-suppressive potential of CMA has been reported in the tumor microenvironment, where CMA is involved in protooncogene proteins such as Murine Double Minute 2 (MDM2) and tumor-associated translationally controlled tumor protein (TCTP) upon acetylation." (PMID 38339390, 2024).